RNU6-581P (RNA, U6 small nuclear 581, pseudogene)
Gene: Small nuclear RNA gene on chromosome 7 (120,672,871 to 120,672,975, forward strand). Ensembl gene ENSG00000252023.
Homologues: Orthologues: chimpanzee U6 (98% identical), macaque U6 (90% identical), guinea pig U6 (72% identical), dog U6 (70% identical), rabbit U6 (69% identical), rat LOC120103217 (69% identical), mouse Gm24468 (67% identical), pig U6 (67% identical). Paralogues in human: RNU6-45P (78% identical), RNU6-509P (78% identical), RNU6-732P (78% identical), RNU6-175P (77% identical), RNU6-242P (77% identical), RNU6-24P (77% identical), RNU6-43P (77% identical), RNU6-820P (77% identical), RNU6-11P (76% identical), RNU6-1243P (76% identical), RNU6-37P (76% identical), RNU6-562P (76% identical), and 1287 more.